VHL (von Hippel-Lindau tumor suppressor)
Diseases named in the same sentence as VHL in open-access papers (continued):
Sharing a sentence is not in itself a finding about the gene and the disease.
von Hippel-Lindau disease (continued). "In addition to the HIF-dependent pVHL functions, the pathophysiology of VHL syndrome could be further explained by the HIF-independent pVHL functions such as extracellular matrix homeostasis maintenance and the direction of microtubule orientation." (PMID 36980956, 2023). "Thus, the most frequent genetic alteration in CCRCC involves chromosome 3p deletion, VHL mutation and/or VHL promoter methylation, leading to VHL inactivation, an early and crucial event in sporadic CCRCC and in the familial cancer syndrome von Hippel–Lindau disease." (PMID 31905821, 2019). "The full gene region for VHL was examined at mosaic detection level, with a clinically actionable mutation identified in 18% of patients with von Hippel-Lindau disease in whom a mutation could not be identified by conventional analysis." (PMID 687517, 2016). "Von Hippel-Lindau disease (VHL; MIM 193300) is an autosomal dominant familial neoplasia syndrome that results from a germline mutation of the VHL gene." (PMID 25276129, 2014). "von Hippel-Lindau disease (VHL) (OMIM no.193300) is an uncommon autosomal dominant cancer syndrome resulting from mutations in the VHL tumor suppressor gene." (PMID 27439424, 2016). "Clear cell RCC is the most common type, accounting for 70-80% of all RCCs, and VHL inactivation is very common in both sporadic clear cell RCC and the hereditary cancer syndrome known as von Hippel-Lindau disease." (PMID 24684806, 2014). "To better understand the molecular landscape of these sporadic tumors, we investigated somatic VHL alterations in 2539 patients with no germline alterations related to VHL syndrome." (PMID 40647474, 2025). "Patient 21 was positive for VHL:c.208G>A with no personal features or tumors of VHL but a first-degree relative diagnosed with VHL syndrome, meeting the criteria for II–VI." (PMID 40647474, 2025). "Hemangioblastomas and ccRCC are relatively common in VHL syndrome, but they are also frequently observed as isolated sporadic tumors in the absence of germline VHL." (PMID 40647474, 2025). "The INT2GRATE results were consistent with these findings, as all VHL variants across 33 individuals in the E1’ region were INT2GRATE Negative, showing the absence of all evidence related to VHL syndrome." (PMID 40647474, 2025). "The review of patient data confirmed this assessment, as the patient was 16 years old and had no VHL personal features yet, but her mother was diagnosed with VHL syndrome." (PMID 40647474, 2025). "One of the major consequences of the lack of a functional VHL protein in von Hippel-Lindau disease, a rare cancer, is the constitutive activation of the HIF pathway." (PMID 31296894, 2019). "Even though clinical criteria for Von Hippel Lindau disease were fulfilled, her VHL genetic test was negative." (PMID 30105106, 2018). "On the other hand, considering the huge number of players involved in VHL syndrome and the lack of reliable kinetic data, a PN based approach may be a preferable option for an entire VHL pathway simulation." (PMID 24886840, 2014). "In our workflow, individuals positive for germline VHL variants who could benefit from somatic tumor evaluation fell in two categories: patients who had tumor(s) that were not component tumors of the VHL syndrome and patients who presented with only one VHL component tumor." (PMID 35774415, 2022). "In VHL, these challenges are further compounded because tumors, such as RCC, that appear in hereditary VHL syndrome can also occur frequently as sporadic tumors without germline involvement." (PMID 40647474, 2025). "Given the rarity of this finding and because PCE could be a manifestation of Von Hippel-Lindau disease (VHL), although the patient had no family or personal history of VHL, the VHL gene was tested, and a known pathogenetic variant (c.464-1G>A; p.)?" (PMID 38162491, 2023).
kidney cancer (139 papers, 2007 to 2026). Primary or metastatic malignant neoplasm involving the kidney. "Clear cell renal cell carcinoma (ccRCC) is a common and aggressive form of kidney cancer with VHL mutations present in > 50% of cases." (PMID 42089431, 2026). "This is clearly inaccurate: CDKN2A and CDK4 (MIM: 123829) PTVs are associated with malignant melanoma, and VHL (MIM: 608537) is associated with kidney cancer." (PMID 40073867, 2025). "Age-related familial risks for breast, prostate and kidney cancers also matched data from large-scale sequencing; these included the early onset component in kidney cancer which was likely due to VHL mutations." (PMID 39985094, 2025). "Loss-of-function germline von Hippel-Lindau (VHL) tumor suppressor mutations cause VHL disease, which predisposes individuals to kidney cancer, hemangioblastomas, and paragangliomas." (PMID 39320914, 2024). "Regarding somatic mutations, VHL has the highest prevalence (43.2%) in the entire population considered from the kidney cancer TCGA dataset (N = 424), followed by PBRM1 and MUC4, both slightly above 20%." (PMID 39199616, 2024). "The most frequently mutated gene in kidney cancer is the von Hippel-Lindau tumor suppressor (VHL) which was detected in 342 (9.77%) out of 3501 cases." (PMID 38132440, 2023). "Clear cell renal carcinoma (ccRCC) is the most common phenotype of kidney cancer, occurring in 70% to 75%, which is strongly associated with von Hippel-Lindau (VHL) gene mutation." (PMID 36765369, 2023). "Kidney renal clear cell carcinoma (KIRC) is the most common type of kidney cancer and its pathogenesis is strongly associated with VHL–HIF–VEGF signaling." (PMID 37964226, 2023). "Afterwards, we analyzed the gene mutations in the high-risk and low-risk groups of the advanced kidney cancer and discovered the mutation of some genes, such as VHL, CHEK2, BAP1, PBRM1, which were closely related to RCC." (PMID 35739510, 2022). "Studies have shown that VHL gene mutations and hypermethylation are widespread in kidney cancer and are related to clinical stage, histological type, and lymph node metastasis." (PMID 35035522, 2022). "The involvement of VHL gene alterations in kidney cancer is confirmed also when inspecting gene mutation counts normalized by gene length." (PMID 35392801, 2022). "As expected, 98% of respondents believed that the approval would lead to a paradigm shift in the management VHL-associated kidney cancer." (PMID 36310638, 2022). "GJB2, MET, MUTYH and VHL mutations ranked top in kidney cancers, and ATM and CHEK2 mutations ranked top for bladder cancer, while ATM and BRCA1 mutations ranked top for prostate cancer." (PMID 36451132, 2022). "According to the TCGA report, the most frequent gene mutations in kidney cancer were VHL, PBRM1, SETD2, and BAP1." (PMID 35055428, 2022). "While the evidences on VHL clearly confirm its involvement in kidney cancer, the other found data-driven associations can be worthy of further investigations." (PMID 35392801, 2022). "In the case of kidney cancer with VHL gene mutation, the overproduction of sphingosine-1-phosphate was reported, as this metabolite can induce proliferation, cell movement, and angiogenesis." (PMID 35967759, 2022). "The genes coding for CRL2pVHL components are known to be frequently altered in cancer, particularly the tumour suppressor gene VHL in kidney cancers, and have been previously associated with cancer progression." (PMID 35664333, 2022). "MiR-210, due to its regulation by HIF-1α a, is of particular importance in kidney cancer for the disruption the HIF-1α/VHL complex formation impaired by frequent VHL mutations in RCC." (PMID 35625614, 2022). "Hypoxia-inducible factor-2α (HIF-2α), a transcription factor, has been shown to accumulate in kidney cancer due to the loss of the VHL gene, causing the activation of downstream messengers, and has been consequently identified as a critical target in RCC." (PMID 35641205, 2022).
kidney cancer (continued). "Mutations of VHL have been proved to be one of the typical genetic causes of kidney cancer, which often lead to stabilization of HIF1α and HIF2α, creating an illusion of pseudohypoxia in stricken renal tissues." (PMID 34193180, 2021). "The most striking genomic discovery in ccRCC is the extreme chromosomal proximity of the four most prevalently mutated kidney cancer TSGs—VHL (~80%), PBRM1 (29-46%), SETD2 (8-30%), and BAP1 (6-19%)—spanning chromosome 3p21-3p25." (PMID 32743344, 2020). "There are many reports on genes associated with kidney cancer pathogenesis, including VHL, FH, MET, FLCN, etc.." (PMID 32850947, 2020). "Of note, the WHO/ISUP kidney cancer grading was also unrelated to presence of VHL mutations and deletions." (PMID 32076485, 2020). "To assay the contribution of HIF-1α to the opposing expression of MISTR1 (NDUFA4) and MISTRH, we leveraged that HIF-signaling is constitutively active in many kidney cancers due to loss of the Von Hippel–Lindau (VHL) tumor suppressor." (PMID 33370271, 2020). "Since up to 90% of kidney tumors harbor VHL functional loss, it remains very attractive to identify synthetic lethality partners in VHL-loss kidney cancer while sparing normal cells." (PMID 29562667, 2018). "While HIF1α serves mainly as a tumor suppressor in kidney cancer, HIF2α stabilization, as a result of VHL loss, is sufficient and necessary in the promotion of kidney tumor growth." (PMID 29562667, 2018). "As VHL mutation is the most common driver of kidney cancer, we asked if elevated DNA methylation was a feature of tumours with mutated VHL." (PMID 30006568, 2018). "The most common molecular markers of kidney cancer include mutations and epigenetic inactivation of von Hippel-Lindau (VHL) gene, genes of vascular endothelial growth factor (VEGF) pathway, and carbonic anhydrase IX (CIAX)." (PMID 26500709, 2015). "In kidney cancer several studies have explored the relation of tumors with mutations in the von-Hippel-Lindau (VHL) gene to risk factors such as history of smoking and hypertension." (PMID 25532962, 2014). "Truncating mutations have also been shown to lead to a higher risk of RCC in VHL patients, and the proband had been diagnosed with kidney cancer." (PMID 24062953, 2013). "In hereditary kidney cancer patients, the inherited germline mutation in one allele of VHL predisposes them to earlier onset bilateral kidney cancer." (PMID 24260413, 2013). "Kidney cancer is associated with several gene mutations including Von-Hippel-Lindau (VHL), fumarate hydratase (FH) and succinate dehydrogenase (SDH) and accounts for 3% of all cancers with 2% of the total cancer deaths in the U.S." (PMID 22804960, 2012). "Inherited germline mutations in VHL predispose hereditary kidney cancer patients, to earlier onset bilateral kidney cancer than sporadic kidney cancer patients, since the loss of the remaining wild type allele occurs more readily than the loss of two alleles." (PMID 21949687, 2011). "This gene is a tumor suppressor, and the loss of a single normal allele was observed in the VHL gene in kidney cancer tissue samples." (PMID 22312516, 2011). "This germline alteration was observed in VHL-associated kidney cancer and is found in nearly 100% of VHL families." (PMID 22312516, 2011). "However, HIF-α deubiquitination does not generally overcome the dominant action of VHL when oxygen is present, and has mostly been observed by overexpression of the DUB, re-oxygenation experiments, or in VHL-deficient kidney cancer cells." (PMID 39009674, 2024). "Consequently, HIF2-α stands out as an important therapeutic target in VHL loss–related kidney cancer." (PMID 38618952, 2024). "Mutations in the VHL gene can lead to the accumulation of hif-2α and subsequently to kidney cancer." (PMID 37305384, 2023).
kidney cancer (continued). "In light of the stimulatory role of VHL deficiency on crystal-induced inflammation and tissue remodeling, our results thus provide a bridge linking the two carcinogenic factors and offer new strategies for the prevention of kidney cancer." (PMID 37833251, 2023). "Moreover, HIF-2α is sufficient to maintain tumor growth in VHL-deficient kidney cancer cells via Cyclin D1 activation." (PMID 36831657, 2023). "Both investigated SNPs can be important prognostic indicators of RCC in the Central European population, because statistically significant associations were observed between evaluated VHL polymorphisms and the best known factors with proven prognostic significance in kidney cancer." (PMID 38115281, 2023). "Notably, aberrant activation of the VEGF-VEGFR axis is a pivotal driver in kidney cancer since more than 60% of patients with kidney cancer harbor VHL mutations." (PMID 36542714, 2022). "Moreover, some tumor types are characterized by mutations leading to widespread metabolic reprogramming (such as IDH1 mutations in glioma and inactivation of the von Hippel–Lindau tumor suppressor in kidney cancer)." (PMID 35565274, 2022). "VHL mutation in kidney cancers is used to be a modulator of oncogenesis." (PMID 34563045, 2021). "The von Hippel Lindau (VHL) tumor suppressor gene, when mutated, is responsible for the VHL disease, a genetic syndrome predisposing to cancer, and plays a critical early role in the development of sporadic kidney cancers." (PMID 33137104, 2020). "Importantly, the VHL gene is also mutated or deleted in 80% of sporadic ccRCC, the most common subtype of kidney cancer." (PMID 33137104, 2020). "Furthermore, the expression levels of prefoldin subunit PFDN3 are critical in kidney cancer patients harboring VHL mutations." (PMID 33137104, 2020). "Hence, generally speaking ccRCC is a VHL-loss kidney cancer, and complete VHL inactivation is the quintessential first functional/genetic truncal event." (PMID 32743344, 2020). "Notably, since the von Hippel Lindau (VHL) gene has an important role in both familial and sporadic kidney cancer, the genes associated with VHL-dependent regulation are important candidates in studying the spectrum of miRNAs that alter VHL expression." (PMID 31110513, 2019). "Notably, more than 90% of the most common form of kidney cancer are associated with bi-allelic somatic mutation in VHL gene." (PMID 31114448, 2019). "To determine whether NleB could GlcNAcylate endogenous HIF-1α, we took advantage of the RCC4 cell line, an VHL-deficient kidney cancer cell line in which HIF-α (HIF-1α and HIF-2α) is highly expressed under normoxia." (PMID 30125331, 2018). "Therefore, HIF2α serves as an important therapeutic target in kidney cancers that are related to VHL loss." (PMID 29562667, 2018). "The exact mechanism of tumorigenesis in HLRCC is unknown, but evidences suggest a pseudo - hypoxic pathway, similarly to the molecular mechanism in VHL - deficient kidney cancer." (PMID 27819754, 2017). "Similarly, the MiSL amplification pipeline uncovered a previously known SL interaction: GLS as a SL partner of the VHL mutation in kidney cancer." (PMID 28561042, 2017). "For KIRC, we assessed whether metastasis, nodal status, stage and presence of Von Hippel-Lindau (VHL) mutation —a common mutation in kidney cancer— were significantly different across the three distinct tumour clusters using multivariate analysis of variance." (PMID 26013764, 2015). "Previous investigations of the molecular epidemiology of kidney cancer have focused attention on cases classified on the basis of mutations in the VHL gene which has been recognized for many years as a source of common early mutations in the development of this disease." (PMID 25532962, 2014). "Indeed, loss of VHL occurs at a very early stage in kidney cancer progression, suggesting that VHL represents the “gatekeeper” gene in this malignancy." (PMID 18047741, 2007).
kidney cancer (continued). "However, the precise mechanisms by which VHL loss promotes the early stages of kidney cancer development remain unclear." (PMID 39451551, 2024). "We explored the potential relationship between VHL, the most common mutation in kidney cancer, and intercellular communication, and then suggested that CCCs could alter the differentiation and infiltration of immune cells, which further influence clinical outcomes of ccRCC patients." (PMID 36765369, 2023). "Therefore, the transcriptomes of tumor cells and infiltrating immune cells may be largely driven by founder variants in kidney cancer associated genes such as VHL and KDM5C." (PMID 35874919, 2022). "Kidney cancer develops in 25%–45% of VHL patients and is uniformly clear cell, bilateral, and multifocal." (PMID 40495894, 2025). "For kidney cancer, a maximum sensitivity and specificity of 88% and 100%, respectively, were found for VHL, p16/CDKN2a, p14ARF, APC, RASSF1A, and Timp-3." (PMID 40141826, 2025). "We discovered that cyclin D1 is the key target of HIF2 driving the cell-autonomous proliferation of VHL-mutant kidney cancers and that cyclin D1 has targets beyond pRB in this setting." (PMID 40178040, 2025). "Previously, we explored the impact of VHL gene inactivation on early-stage kidney cancer, focusing on inflammation through the activation of the IRE1α signaling pathway associated with endoplasmic reticulum stress." (PMID 39451551, 2024). "While our studies directly tested a role for VHL, Renca cells are derived from spontaneously arising murine kidney cancer, in which they were established as VHL WT." (PMID 38618956, 2024). "Among the top 10 mutated genes found in the kidney cancer dataset, PBRM1, BAP1, SETD2, and VHL have been implicated in tumor progression and poor prognoses." (PMID 39199616, 2024). "By examining the impact of VHL on the early stages of kidney cancer development, this research highlights the contributions of inflammation and ROS, as well as the involvement of Lon protease." (PMID 39451551, 2024). "ccRCC is the most prominent subtype of kidney cancer, where inactivation of VHL tumor suppressor gene is regarded as the governing event for progressing through HIF transcription factor activation in conventional ccRCC." (PMID 38680858, 2024). "Mutational inactivation of the VHL tumor suppressor gene causes an inappropriate accumulation of HIF, which promotes tumorigenesis in the context of kidney cancer." (PMID 37445575, 2023). "There is a clear relationship between the prevalence of kidney cancer and VHL genotype, with a higher prevalence in patients with partial deletion of the VHL gene." (PMID 36672305, 2023). "Using a new technology to measure the ribosome load of mRNAs resolved by their TSS, we have characterized the pan-genomic interplay of HIF- and mTOR-dependent transcriptional and translational regulation in VHL-defective kidney cancer cells." (PMID 36097292, 2022). "Research has found that the VHL gene-hypoxia-inducible factor-hypoxia response gene pathway (VHL-HIF-HRG pathway) plays an important role in kidney cancer." (PMID 35035522, 2022). "We applied ultrasound microbubble method to transfect VHL plasmid into human kidney cancer cell lines, applied RT-PCR method to detect the expression of the VHL gene, MTT to detect cell proliferation ability, and flow cytometer to detect apoptosis rate." (PMID 35035522, 2022). "It further confirmed the important role of the VHL gene in the occurrence and development of human kidney cancer, and provided an experimental basis for gene therapy of kidney cancer." (PMID 35035522, 2022). "Overall, these findings indicate that full upregulation of the glycolysis pathway requires both HIF and mTOR activity, as would be predicted to occur in VHL-defective kidney cancer with mTOR hyperactivation." (PMID 36097292, 2022). "The incidence of kidney cancer involves multiple genes, of which the Von Hippel-Lindau (VHL) gene is most closely related to kidney cancer." (PMID 35035522, 2022).